SP3 (Sp3 transcription factor)
Diseases named in the same sentence as SP3 in open-access papers (continued):
Sharing a sentence is not in itself a finding about the gene and the disease.
osteosarcoma (2 papers, 2013 to 2016). A usually aggressive malignant bone-forming mesenchymal neoplasm, predominantly affecting adolescents and young adults. "A study showed that Sp3 mediates transcriptional activation of the p21WAF1/KIP1 gene promoter in osteosarcoma cells by HDAC inhibition." (PMID 27716272, 2016). "We subsequently confirmed the binding of Sp1 and Sp3 using nuclear extracts from the chondrosarcoma cell line SW1353, the osteosarcoma cell line MG63 and from primary human articular chondrocytes (HACs)." (PMID 23825960, 2013).
ovarian carcinoma (2 papers, 2012 to 2016). A malignant neoplasm originating from the surface ovarian epithelium. "SP3-CTP was leveraged to generate the first in-depth quantitative proteome analysis of ovarian carcinoma histotype variation from clinical FFPE tissue samples." (PMID 27713570, 2016). "Taken together, these data demonstrate the orthogonal nature of the proteome data with established genome and transcriptome screens, and highlight the ability of SP3-CTP to yield actionable protein features with potential clinical relevance in the context of ovarian carcinoma." (PMID 27713570, 2016). "The correlation in global expression between SP3-CTP derived protein and RNA in the ovarian carcinoma histotype data was modest, with the highest agreement in the HGSC vs. CCC comparison." (PMID 27713570, 2016). "Topological analysis of the network reveals a set of 15 target genes that are regulated by SP3 or NFκB1 in normal cells, but by E2F1 in ovarian cancer." (PMID 22548828, 2012). "Neither angiogenesis nor the transcription factors E2F1, SP3 and NFκB1 were identified in the original analysis of the ovarian cancer data." (PMID 22548828, 2012). "Although the analysis of 5 HGSC and 5 CCC tumours displayed established patterns of protein expression characteristic of ovarian cancer histotypes, it remained unclear whether the FFPE treatment of the material inhibited accurate in-depth quantitative proteome analysis with SP3-CTP." (PMID 27713570, 2016). "Topological analysis of the complete network also suggests cross-regulation of angiogenesis-specific genes through SP3, NFκB1 and E2F1 in the normal and ovarian cancer networks, and we hypothesize that deregulation of these angiogenic genes may be associated with oncogenesis." (PMID 22548828, 2012).
prostate tumor (2 papers, 2012 to 2015). "Expression of Sp1 and c-FLIP are elevated while AKR1C1, ERβ and Sp3 are significantly low in human prostate tumor samples." (PMID 25816367, 2015). "We also compared the expression of AKR1C1, c-FLIP, Sp1, Sp3 and ERβ in human prostate tumors and normal tissue from oncomine, cancer-profiling database." (PMID 25816367, 2015). "Furthermore, we also showed that FLIP is regulated transcriptionally through modulation of the transcription factors Sp1 and Sp3 and that inhibition of FLIP prevented prostate tumor development in a preclinical animal model." (PMID 23028678, 2012). "However, to the best of our knowledge no studies have examined the expression of Sp1 and Sp3 in human prostate tumors." (PMID 25816367, 2015).
soft tissue sarcoma (2 papers, 2013 to 2019). A malignant neoplasm arising from muscle tissue, adipose tissue, blood vessels, fibrous tissue, or other supportive tissues excluding the bones. "Of note, upregulation of Sp3 expression in soft tissue sarcoma (STS) compared to normal connective tissue has been confirmed in the web database ONCOMINE." (PMID 31533233, 2019). "Considering that Sp3 is expressed at higher levels in soft tissue sarcomas and transactivates the AFAP1L1 gene, targeting Sp3 could be a powerful approach to treating advanced soft tissue sarcomas." (PMID 23326307, 2013).
acute myeloid leukemia (1 paper, 2012). Acute myeloid leukemia (AML) is a group of neoplasms arising from precursor cells committed to the myeloid cell-line differentiation. "SP3, a nuclear protein identified in numerous different biochemical assays at translocation break points, is associated with a subtype of acute myeloid leukemia." (PMID 22830977, 2012).
Alzheimer disease (1 paper, 2023). A progressive, neurodegenerative disease characterized by loss of function and death of nerve cells in several areas of the brain leading to loss of cognitive function such as memory and language. "In Alzheimer's disease tissues and models, the interactions between Sp3 and HDAC2 regulate synaptic plasticity via repression of multiple transcripts involved in synapse formation." (PMID 36762637, 2023).
aneurysm (1 paper, 2024). Bulging or ballooning in an area of an artery secondary to arterial wall weakening. "Thoracic aneurysm SMCs also shared TFs with abdominal aneurysm SMCs, including Jun and Sp3, which may be signals specific to aneurysm formation." (PMID 39590192, 2024).
asthma (1 paper, 2025). "Many of them have been associated with asthma regulation, mainly SP3 and KLF15." (PMID 41154593, 2025).
atherosclerosis (1 paper, 2026). A disease characterized by the build-up of fatty material and calcium deposition in the arterial wall resulting in partial or complete occlusion of the arterial lumen. "Targeting SP3/NEU3 seems to be a potential therapeutic strategy for such diseases with Neu5Ac accumulation like atherosclerosis (AS)." (PMID 42117319, 2026).
autoimmune disease (1 paper, 2011). A disorder resulting from loss of function or tissue destruction of an organ or multiple organs, arising from humoral or cellular immune responses of the individual to their own tissue constituents. "During this maturation process, a transition from SP3 to SP4 was found to be critical as a blockage of this transition in Aire-/- and Relb-/- mice is associated with high incidence of autoimmune diseases." (PMID 22022412, 2011).
Autoimmunity (1 paper, 2011). The occurrence of an immune reaction against the organism's own cells or tissues. "Similarly, defects in the thymocytes-epithelial cells interaction in the medulla, such as Aire and Relb deficiency, result in the SP3-to-SP4 blockage and autoimmunity in the periphery." (PMID 22022412, 2011).
bronchioloalveolar carcinoma (1 paper, 2009). A well or moderately differentiated morphologic variant of lung adenocarcinoma characterized by tumor growth along the alveolar structures without stromal, vascular, or pleural invasion. "Moreover, genistein can block the stimulation of VEGF gene transcription by all trans-retinoic acid through Sp1 and Sp3 sites in a human bronchioloalveolar carcinoma cell." (PMID 19742137, 2009).
B‐cell lymphoma (1 paper, 2021). "Moreover, engineered SP3 promoter hypermethylation led to transcriptional suppression in human B lymphocytes and induced B‐cell lymphoma." (PMID 36618443, 2021).
cervical cancer (1 paper, 2014). A primary or metastatic malignant neoplasm involving the cervix. "In the present study, Sp3 was downregulated in the OC group, which may contribute to the increased incidence of cervical cancer through pathways including hTERC." (PMID 25109897, 2014).
chondrosarcoma (1 paper, 2013). A malignant cartilaginous matrix-producing mesenchymal neoplasm arising from the bone and soft tissue. "In line with that observed in SW872 cells, the increases in GDF5 expression were not significant following Sp1, Sp3 and P15 depletion but a significant fold change was observed upon DEAF-1 knockdown in this chondrosarcoma cell line." (PMID 23825960, 2013).
colitis (1 paper, 2022). Inflammation of the colon. "Compared with the other two groups, TLR5 and the potential transcription factor Sp3 were reduced in the epithelial cells of mice with DSS-induced colitis." (PMID 35893896, 2022).
diabetes (1 paper, 2021). "rs163184 is a diabetes susceptibility polymorphism located in the TFBS of Sp3." (PMID 33919522, 2021).
emphysema (1 paper, 2020). "The data suggest strain-specific effects on emphysema development with more noticeable effects for the 106.66 strain (Sp1) and its capsule mutant (Sp3)." (PMID 33295863, 2020). "Our data suggest that the capsule type has less importance in enhancing smoke-induced emphysema as the two strains with the 106.66 backbone (Sp1 and Sp3) tended to have higher Lm values regardless of capsule type." (PMID 33295863, 2020).
endothelial dysfunction (1 paper, 2023). In vascular diseases, endothelial dysfunction is a systemic pathological state of the endothelium (the inner lining of blood vessels) and can be broadly defined as an imbalance between vasodilating and vasoconstricting substances produced by (or acting on) the endothelium. "To further explore the molecular mechanism by which Sp1 and Sp3 regulate endothelial function, we used Ang II, implicated in the pathogenesis of endothelial dysfunction, as a representative stimulus." (PMID 37735515, 2023). "The activity of the antioxidant N-acetyl-L-cysteine (NAC) decreased the protein levels of Sp1 and Sp3 induced by Ang II, which suggests that Ang II aggravated endothelial dysfunction by promoting reactive oxygen species (ROS) and reducing Sp1 and Sp3 expression." (PMID 37735515, 2023). "Taken together, these data indicate that Sp1 and Sp3 deletion abolished the captopril-induced alleviation of endothelial dysfunction and the anti-apoptotic effects of captopril in endothelial cells; Sp1 and Sp3 have an indispensable role in the success of captopril treatment in the endothelium." (PMID 37735515, 2023).
glioblastoma (1 paper, 2016). The most malignant astrocytic tumor (WHO grade IV). "Levels of MAOB are correlated by the levels of transcription factor Sp3 in the majority of GBM examined, but this control of MAOB expression by Sp3 in low grade astrocytic gliomas is significantly different from control in the in the majority of glioblastomas." (PMID 26689994, 2016).
head and neck cancer (1 paper, 2013). A primary or metastatic malignant neoplasm affecting the head and neck. "A recent report demonstrated the expression of Sp3 to be an independent prognostic factor for the poor survival of head and neck cancer patients." (PMID 23326307, 2013).
HIV-1 infection (1 paper, 2022). The type species of lentivirus and the etiologic agent of acquired immunodeficiency syndrome (AIDS). "It is more likely, though, that miR-223 influences HIV-1 infection by targeting cellular factors required for replication, such as ras homolog family member B (RhoB), Sp3 transcription factor (Sp3), and leukemia inhibitory factor (LIF)." (PMID 36142450, 2022). "This miRNA may also function as a positive factor in HIV-1 infection by targeting HIV-1-suppressive Sp3 and LIF." (PMID 36142450, 2022).
Hyperglycemia (1 paper, 2020). An increased concentration of glucose in the blood. "For instance hyperglycemia promotes the methylglyoxal modification of mSin3A in ECs, triggering increased O-GlcNAcylation of the transcriptional regulator Sp3 via recruitment of OGT." (PMID 33086728, 2020). "Hyperglycemia promotes the modification of the transcriptional regulator mSin3A by methylglyoxal in endothelial cells (ECs), triggering the increased O-GlcNAcylation of another transcriptional regulator, Sp3, via recruitment of OGT." (PMID 33086728, 2020).
hyperinsulinism (1 paper, 2017). Abnormally high levels of insulin in the blood. "We noticed that another member of the SP family, SP3, is also predicted by GLADIATOR to participate in the hyperinsulinism module, and found that a recent study suggests a new mechanism involving both SP1 and SP3 in mediating insulin activation of glucokinase transcription." (PMID 28549478, 2017).
ischemia (1 paper, 2023). A hypoperfusion of the BLOOD through an organ or tissue caused by a PATHOLOGIC CONSTRICTION or obstruction of its BLOOD VESSELS, or an absence of BLOOD CIRCULATION. "The loss of Sp1/Sp3 delayed the angiogenesis in neonatal retinas, reparative angiogenesis to hindlimb ischemia and skin wound, even the angiogenesis in the subcutaneous tumor." (PMID 37735515, 2023).
kidney failure (1 paper, 2023). An acute or chronic condition that is characterized by the inability of the kidneys to adequately filter the blood. "In the same consortium, an analysis stratified by gender identified a variant between the SP3 and CDCA7 genes associated with kidney failure in women (rs4972593, p-value = 3.9 × 10−8)." (PMID 37324271, 2023). "Furthermore, the Sp3 transcription factor directly interacts with the estrogen receptor-α and regulates kidney-related genes such as TGFBI, CD2AP, and VEGFA, supporting its role in kidney failure in women with T1D." (PMID 37324271, 2023).
Listeria monocytogenes infection (1 paper, 2011). "When the same number of purified SP3, SP4 thymocytes and naïve CD4+ T cells from C57BL/6 Ly5.1 mice were adoptively transferred into congenic Ly5.2 mice, similar levels of donor T cell activation were observed seven days after Listeria monocytogenes infection of the host." (PMID 22022412, 2011).
liver cancer (1 paper, 2015). An epithelial or non-epithelial malignant neoplasm that arises from the liver. "Regulation of HULC by Sp1, Sp3 and Sp4 in liver cancer cells was investigated by RNAi with oligonucleotides that targeted the individual Sp transcription factors." (PMID 26317792, 2015). "RNA interference (RNAi) studies showed that among several lncRNAs expressed in HepG2, SNU-449 and SK-Hep-1 cells, highly upregulated in liver cancer (HULC) was regulated not only by Sp1 but also Sp3 and Sp4 in the three cell lines." (PMID 26317792, 2015).
metabolic syndrome (1 paper, 2017). A cluster of metabolic risk factors for CARDIOVASCULAR DISEASES and TYPE 2 DIABETES MELLITUS. "If Sp1, Sp3, NF-kappaB, and VDR are increased in obese and T2D subjects, then this could be a mechanism underlying the elevated expression of ADAM19 in the metabolic syndrome." (PMID 28265178, 2017).
monocytic leukemia (1 paper, 2024). "The deletion or mutation of the CT element required for the binding of transcription factors SP1 and SP3 in the human lipoprotein LPL promoter led to a reduction of about 70–80% in promoter activity in a human monocytic leukemia cell line." (PMID 39590382, 2024).
mycoplasma infection (1 paper, 2025). "The results revealed that as the multiplicity of infection increased, the luciferase signal also increased, indicating that mycoplasma infection can increase the expression of PADI2 through the SP3 transcription factor." (PMID 41146353, 2025).
myocardial infarction (1 paper, 2018). Gross necrosis of the myocardium, as a result of interruption of the blood supply to the area, as in coronary thrombosis. "The reduced binding affinity of Sp1/Sp3 in the presence of the T allele of the tissue-type plasminogen activator –7351C > T polymorphism explained an increased risk of myocardial infarction in individuals carrying this allele." (PMID 30413149, 2018). "Transcription factor Sp3 is suggested in our study as associated with myocardial infarction, but we cannot exclude that other TFBS, shown as related to RXRA SNPs, are also associated with this phenotype." (PMID 30413149, 2018).
nasopharyngeal carcinoma (1 paper, 2025). A carcinoma arising from the nasopharyngeal epithelium. "The expression of specificity protein 1 (Sp1) and Sp3 is significantly increased in nasopharyngeal carcinoma cells." (PMID 40071086, 2025). "Inhibiting the activities of Sp1 or Sp3 can reduce the level of CENP-H, thus affecting the growth of nasopharyngeal carcinoma." (PMID 40071086, 2025).
neuroblastoma (1 paper, 2020). Neuroblastoma (NB) is the most common solid, extracranial childhood tumor. "According to previous findings, miR-380–3p regulated by Nrf2 suppressed cell proliferation and strengthened the PQ-induced toxicity in mouse neuroblastoma cells via obstructing Sp3 mRNA translation." (PMID 32811810, 2020).
ovarian tumours (1 paper, 2019). "In contrast SP3 expression level was significantly lower in ovarian tumours than in control ovarian tissue." (PMID 31362717, 2019). "On the other hand, ovarian tumours were characterized by significantly lower level of SP3 transcripts." (PMID 31362717, 2019). "However, ovarian tumours were characterized by significantly lower SP3 expression than control ovarian tissue (p < 0.01)." (PMID 31362717, 2019).
rectal cancer (1 paper, 2017). A primary or metastatic malignant neoplasm that affects the rectum. "The results showed that E2F4 and SP3 correlated significantly with POFUT1 and PLAGL2 in colon and rectal cancer, which indicated E2F4 and SP3 are the most likely transcription factor binding to this bidirectional promoter and causing co-expression of the gene pair." (PMID 29108255, 2017).
renal fibrosis (1 paper, 2025). A final common manifestation of a wide variety of chronic kidney diseases characterized by glomerulosclerosis and tubulointerstitial fibrosis. "Moreover, SP3 exhibits a close connection with renal fibrosis." (PMID 39850832, 2025).
retinitis (1 paper, 2022). Inflammation of the retina. "In contrast, only two of the three UL40 peptides, VMAPRTLIL (SP1) and VMAPRTLVL (SP3), were observed in the majority of intraocular fluid specimens from CMV-retinitis patients (in which one of the peptides was observed in each patient), and VVAPRTLIL (SP2) was not present in their ocular fluid." (PMID 36341392, 2022).
T-cell lymphoma (1 paper, 2022). "To examine the association between apoptosis and Sp3 cleavage in KSHV-negative cells, we used Jurkat cells, a human T-cell lymphoma cell line, as a model system." (PMID 35019687, 2022).
Thrombocytopenia (1 paper, 2019). A reduction in the number of circulating thrombocytes. "Interestingly, megakaryocyte specific knockout of Sp1/Sp3 transcription factors display thrombocytopenia and platelet dysfunction in mice." (PMID 30894555, 2019).
type 2 diabetes (1 paper, 2025). "In adipocyte 2, transcription factors associated with neurodegenerative diseases, type 2 diabetes, and cancer (Ctcfl, Etv3, Atf4, Zmiz1, Sp3) showed reduced activity in the old group." (PMID 40631796, 2025).